MYCN (MYCN proto-oncogene, bHLH transcription factor)
Diseases named in the same sentence as MYCN in open-access papers (continued):
Sharing a sentence is not in itself a finding about the gene and the disease.
neuroblastoma (continued). "MYCN-amplified neuroblastoma cells need an efficient machinery to meet the metabolic demands to keep enough amount of glutamine, which is a process which strictly relies on the interaction of specific amino acid transporters." (PMID 32547946, 2020). "The comprehensive genome-wide analysis performed here allowed us to discover age-associated alterations in MYCN, TERT, PTPRD, and Ras pathway alterations, which together with ATRX represent the majority of common driver gene alterations in neuroblastoma." (PMID 33056981, 2020). "A recent study revealed that ALDH18A1 formed a positive feedback loop with MYCN and was involved in the malignant transformation of neuroblastoma cells." (PMID 33194665, 2020). "Neuroblastoma patients with MYCN amplification also demonstrated worse clinical outcomes in GSE85047 dataset." (PMID 32593299, 2020). "MYCN enables neuroblastoma cells to oxidize fatty acids with a higher capacity than in non-MYCN amplified cells." (PMID 33585251, 2020). "MYCN downregulation broadly reverses tumor stem-like phenotypes and aberrant cell cycle in a variety of neuroblastoma models." (PMID 32054830, 2020). "A recent study reported that, in ALK mutant, MYCN amplified neuroblastomas, resistance to ALK inhibitors is accompanied by a decrease in MYCN expression and upregulation of the brother of the regulator of imprinted sites (BORIS) protein." (PMID 33291749, 2020). "We also tested the ability of BioBombe features to distinguish MYCN amplification in neuroblastoma (NBL) tumors." (PMID 32393369, 2020). "MYCN expression is downregulated by 13-cisRA, a differentiating agent that is a component of neuroblastoma therapy." (PMID 32409685, 2020). "Amplification of MYCN is found in about 25% of neuroblastoma, the most common extracranial solid tumor of childhood, and correlates with poor outcome." (PMID 32415090, 2020). "High MYCN expression occurs in about 20% of neuroblastoma and is a clear indication of bad prognosis." (PMID 33233777, 2020). "In the previous report, P22077 significantly suppressed the growth of human neuroblastoma cell lines which MYCN was amplified." (PMID 32002017, 2020). "Ectopic MYCN caused metabolic reprogramming, mitochondrial dysfunction, ROS production, and DNA damage in ATRX-mutant neuroblastoma cells." (PMID 32060267, 2020). "Novel, selective inhibitors of USP7, USP7-055, and USP7-797, have been developed recently for tumor therapy including MYCN-amplified neuroblastoma." (PMID 33614505, 2020). "While the MYCN-NA neuroblastoma analysis above focused on immune and wound healing expression signatures, the hydra enrich method is unsupervised and can therefore detect any type of expression signature." (PMID 32275708, 2020). "A recent study based on the modeling of miRNA-mRNA interactions identified a regulatory loop between MYCN and miR-204 in neuroblastoma cells." (PMID 33937011, 2020). "Amide 11 decreased MycN levels concomitantly with a decrease of CRABP-II in neuroblastoma IMR-32 cells, whereas 11 hardly inhibited proliferation of HT1080 and MCF-7 cells, which express CRABP-II and cIAP1, but not MycN." (PMID 32326273, 2020). "In neuroblastoma primary tumors with low MYCN, tumors with high c-MYC protein had a trend of higher MK2 protein expression relative to those with low MYCN and c-MYC proteins." (PMID 32409685, 2020). "Together, these data show that CAMKV is a membrane-bound protein in MYCN amplified neuroblastoma with the potential to be targeted using a CAMKV-specific biologic." (PMID 32211329, 2020). "A covalent inhibitor of CDK7, THZ1, selectively targets MYCN-amplified neuroblastoma cells, leading to global suppression of MYCN-dependent transcriptional amplification and sustained growth inhibition of tumors in a mouse model of neuroblastoma." (PMID 33614505, 2020).
neuroblastoma (continued). "mRNA expression of the PARP family of proteins has been correlated with MYCN amplification prognosis in neuroblastoma and here we provide in vitro evidence that PARP1 protein and PAR activity is increased in association with MYCN expression." (PMID 32577161, 2020). "The neural crest derived neuroblastomas acquired copy number gains and losses that are similar to those observed in human MYCN-amplified neuroblastoma." (PMID 33585251, 2020). "A plethora of studies have described the functional interconnection between miRNAs and MYCN in neuroblastoma." (PMID 33937011, 2020). "For metabolic profiling of these conditions, we chose SHEP neuroblastoma cells, in which we had previously noticed MYCN-induced HK2 upregulation indicating metabolic reprogramming." (PMID 32346009, 2020). "The most common chromosomal aberration related to poor prognosis in neuroblastoma is somatically acquired segmental gain of 17q, hemizygous deletions of 1p and 11q, and MYCN gene amplification." (PMID 33585251, 2020). "Currently, the amplification of MYCN is still one of the most risky genetic markers in neuroblastoma." (PMID 32963529, 2020). "Consistent with our findings, the authors identified a region overlapping e4 that was significantly co-amplified in MYCN-amplified neuroblastomas, corresponding to class I amplicons observed in our cohort." (PMID 33199677, 2020). "More strikingly, we found that high tumor PLAGL2 mRNA levels were significantly correlated with high MYCN mRNA levels and poor patient survival in neuroblastoma patients." (PMID 32087738, 2020). "In neuroblastoma, the expression levels of MYCN are strongly correlated with those of ODC1, and high levels of ODC1 driven by MYCN amplification and overexpression are strongly associated with poor clinical outcome in NB patients." (PMID 33628735, 2020). "This interplay provides a possible mean to develop novel strategies to target the MYCN pathway for treating neuroblastoma." (PMID 32087738, 2020). "MYCN-amplified neuroblastoma cells exhibit enhanced expression of genes and proteins involved in aerobic glycolysis (Warburg effect), oxidative phosphorylation (OXPHOS), detoxification of reactive oxygen species (ROS), and FAO." (PMID 32547946, 2020). "The neuroblastoma cancer research has long been focused on the role of MYCN oncogene amplification and the contribution of other genetic alterations in the progression of this malignancy." (PMID 32722460, 2020). "LIN28B, an RNA-binding protein and a suppressor of microRNA biogenesis, selectively blocks the biogenesis of let-7 miRNA, consequently leading to increased MYCN expression in neuroblastoma cells." (PMID 33614505, 2020). "In neuroblastoma, NK cell-derived exosomes carrying the tumor suppressor miR-186 are cytotoxic to MYCN-amplified neuroblastoma and inhibit tumor escape mechanisms." (PMID 33168028, 2020). "The proteasome inhibitor alters cellular protein homeostasis and has shown to prevent MYCN degradation resulting in its accumulation with a deleterious effect in MYCN-driven neuroblastomas." (PMID 32971811, 2020). "When trained with different latent dimensionalities, models learn strongly associated and generalizable biological representations including sex, neuroblastoma MYCN amplification, and cell types." (PMID 32393369, 2020). "MYCN-amplified neuroblastoma (NB) cells exhibit transcriptional activation of human telomerase reverse transcriptase (hTERT) expression." (PMID 32637577, 2020). "Accordingly, the FAO inhibitor etomoxir, which inhibits the rate-limiting FAO enzyme carnitine palmitoyltransferase 1 (CPT1C), suppresses the growth of xenograft tumors derived from MYCN-amplified neuroblastoma." (PMID 32547946, 2020). "Because most mitochondrial proteins are overexpressed in MYCN-amplified neuroblastoma, and OXPHOS results in the production of intracellular ROS in mitochondria, the members of the peroxiredoxin ROS scavenger system, such as peroxiredoxin 6, are upregulated." (PMID 32547946, 2020).
neuroblastoma (continued). "The observed associations between specific NME1 overexpression with other markers of poor patient prognosis such as MYCN amplification reinforces our suggestion that histidine-dependent signaling is likely to be involved in neuroblastoma pathogenesis." (PMID 32392889, 2020). "In another interesting study by Neviani and colleagues, the tumor-suppressor miR-186 was detected in natural killer cell-derived exosomes, which exhibited cytotoxicity against neuroblastoma cells with high MYCN levels." (PMID 33937011, 2020). "Pharmacological inhibition of the AKT/mTOR pathway reduces N-MYC level and exhibits therapeutic efficacy in MYCN-amplified neuroblastoma." (PMID 33614505, 2020). "Amplification of MYCN in neuroblastoma tumors correlates with high VRK1 gene expression and aggressiveness, although the levels of VRK1 do not correlate with the levels of MYCN expression in nonamplified tumors." (PMID 33233777, 2020). "PERK inhibition with an optimized kinase inhibitor, GSK2606414, reduces autophagy in MYCN‐amplified neuroblastoma cells and further enhances the efficacy of GLI inhibitor in repressing the growth of these cells in vitro and in vivo." (PMID 32310340, 2020). "In conclusion, miR-145 was low expressed in high-risk MYCN amplified (MNA) neuroblastoma, and low miR-145 expression was associated with worse survival in patients with neuroblastoma." (PMID 32083506, 2020). "CYC065, used together with temozolomide, a reference therapy for relapsed neuroblastoma, caused long-term suppression of neuroblastoma growth in vivo, highlighting the clinical potential of CDK9/2 inhibition in the treatment of MYCN-amplified neuroblastoma." (PMID 33016930, 2020). "The objective of the present investigation was to explore role of RNA N6-methyladenosine modification in miR-98/MYCN axis-mediated inhibition of neuroblastoma progression." (PMID 32788584, 2020). "More importantly, Yoko’s study has found that SMC2 was transcriptionally regulated by MYCN, a carcinogenic gene with poor prognosis in MYCN-amplified neuroblastoma cells." (PMID 32586319, 2020). "Here, we seek out to identify key regulatory elements near MYCN in neuroblastoma by integrating short- and long-read genomic and epigenomic data from neuroblastoma cell lines and primary tumors." (PMID 33199677, 2020). "We then demonstrated for the first time that combined glutamine deprivation with irradiation led to a selective radioresistance of MYCN-amplified neuroblastoma cells." (PMID 32483461, 2020). "One patient from the DG was diagnosed in 2016 of a multifocal relapse of a stage 4, MYCN amplified neuroblastoma." (PMID 32549040, 2020). "Most genes in ribosome signaling pathway were up-regulated in MYCN amplified neuroblastoma patients, as demonstrated the RPS19 expression levels in TARGET, GSE19274, GSE49710, GSE73517 and GSE85047 datasets." (PMID 32593299, 2020). "In the current study, we highlighted the possible role of CEP131 on replication stress (RS) in MYCN-amplified neuroblastoma NB-39-nu cell line." (PMID 33014050, 2020). "Althoff et al23 reported that miR‐542‐3p expression was downregulated in late‐stage, high‐grade, and MYCN‐amplified neuroblastoma." (PMID 32167655, 2020). "MYCN‐amplified neuroblastoma cells (KELLY) were injected into the left gland of mice to generate an orthotopic neuroblastoma model." (PMID 32096344, 2020). "An unbiased screen of 673 genetically characterized tumor-derived cell lines shows that neuroblastoma cell lines with MYCN amplification are more sensitive to JQ1 treatment compared to MYCN-wild-type tumors." (PMID 33628735, 2020). "miR-204 directly binds MYCN mRNA, represses MYCN expression, and inhibits a subnetwork of oncogenes that strongly correlate with MYCN-amplified neuroblastoma and poor patient outcome." (PMID 33614505, 2020).
neuroblastoma (continued). "Transcription factor ChIP-seq in MYCN-expressing cells confirmed that four of the enhancers (e1, e2, e4, and e5) were bound by each of three noradrenergic neuroblastoma core regulatory circuit transcription factors (PHOX2B, HAND2, GATA3)." (PMID 33199677, 2020). "We focused on the MYCN-NA neuroblastoma tumor samples because this is the largest set of samples (N = 70) and variation within MYCN-NA tumors is not well understood." (PMID 32275708, 2020). "Using the clinical data deposited in TARGET dataset, we analyzed the prognosis of MYCN amplification in patients with neuroblastoma." (PMID 32593299, 2020). "Our previous work demonstrated critical roles of PRMT1 and PRMT5 for neuroblastoma cell growth in part through arginine methylation of MYCN and subsequent enhancement of its stability." (PMID 32415090, 2020). "Studies found that in neuroblastoma, the relationship between MYCN amplification and cell activity and aggressiveness suggests a potential relationship between focal adhesion kinase (FAK) and MYCN, since FAK is a key protein involved in cell activity." (PMID 33381457, 2020). "GLDC contributes to metabolic reprogramming exclusively in MYCN-amplified neuroblastoma cells, as demonstrated by the effect of GLDC knockdown on central carbon metabolism pathways, including glycolysis and the TCA cycle, as well as lipid synthesis." (PMID 32547946, 2020). "MYCN-amplified neuroblastoma cells show high levels of CPT1C expression, and inhibition of both CPT1C and peroxisomal β-oxidation leads to lipid accumulation." (PMID 32547946, 2020). "Our group previously identified miR-506-3p as a potent differentiation inducer and a strong repressor of MYCN expression in neuroblastoma cells." (PMID 32087738, 2020). "The result of SA-β-gal staining indicated that exogenous MYCN expression weakened the occurrence of senescence, indicating that MYCN degradation resulting from AURKA inhibition is a possible cause of neuroblastoma cellular senescence." (PMID 31920463, 2020). "Two additional human paralogs were eventually identified: MYCN (N-Myc) initially observed in neuroblastoma, and MYCL (L-Myc) identified in lung cancer samples." (PMID 32331235, 2020). "Neither is it known in detail how and in which cell type the expression of MYCN is initiated in order to drive neuroblastoma tumorigenesis." (PMID 33585251, 2020). "Signature 18 is enriched in neuroblastomas with MYCN amplification, 17q gain, and increased expression of mitochondrial ribosome and electron transport-associated genes." (PMID 33056981, 2020). "MYCN is expressed at the highest levels in neuroblastomas harboring MYCN amplifications, with a strong effect of genomic copy number on expression levels." (PMID 33199677, 2020). "Our analysis found significant variation in immune marker expression, including markers of response to checkpoint blockade therapy, and identified ATRX deletions as a potential biomarker of immune infiltrated tumors in MYCN-NA neuroblastoma." (PMID 32275708, 2020). "MYCN-induced glutaminolysis in neuroblastoma elevates reactive-oxygen species (ROS) and DNA-replicative stress." (PMID 32060267, 2020). "We next assessed a second MYCN-amplified (MNA) neuroblastoma cell-line, IMR32, confirming the growth-inhibitory effects of BMP4, with the lowest significant effect observed at 5 ng/mL." (PMID 32210188, 2020). "We investigated the clinical relevance of PLAGL2 expression by examining the correlation of tumor PLAGL2 mRNA levels with MYCN mRNA expression and patient survival using public neuroblastoma patient datasets." (PMID 32087738, 2020). "MYCN oncogene is a characteristic feature of an advanced and aggressive neuroblastoma stage, representing a poor prognosis." (PMID 32823876, 2020).
neuroblastoma (continued). "In the GSEA assay, we identified 75 MYC target genes which were up-regulated in MYCN amplified neuroblastoma tissues in TARGET dataset." (PMID 32593299, 2020). "We also constructed a gene set based on a functional neuroblastoma-specific MYCN signature of 157 genes whose up- or down-regulation in IMR32 cells had been demonstrated to be strongly linked with neuroblastoma prognosis (MYCN157)." (PMID 32210188, 2020). "In human neuroblastoma, amplification of the MYCN gene predicts a poor prognosis and resistance to therapy." (PMID 31920463, 2020). "MYCN-mediated hyperproliferation signals increase the level of RS stress in neuroblastoma cells, thus rendering them reliant on CHK1 function to ensure their acceptable genome duplication cycles." (PMID 33014050, 2020). "MYCN overexpression in mesenchymal neuroblastoma was sufficient to induce adrenergic identity and sensitize cells to CYC065." (PMID 33016930, 2020). "A recently defined subset of high-risk neuroblastoma tumors that lack MYCN amplification overexpress the MYC protein and have a poor prognosis comparable to those with amplified MYCN." (PMID 32211329, 2020). "The level of differentiation and tumor location resemble the human neuroblastoma more in the LSL-MYCN;Dbh-iCRe than in the Th-MYCN model." (PMID 33585251, 2020). "Neuroblastoma patients were divided into four sub-groups based on MYCN status and EIF4G1 mean expression level in TARGET and GSE85047 datasets." (PMID 32593299, 2020). "There was a partial rescue of cell death in SKNMMMYCN cells in the presence of doxycycline when CUX2 was ectopically expressed, suggesting that CUX2 is important for oxidative stress in MYCN-amplified neuroblastomas." (PMID 32060267, 2020). "MYCNOS1 transcripts regulate MYCN post-transcriptionally, affecting the levels of MYCN protein, whereas regulation at the transcriptional or posttranscriptional levels has been described for MYCNOS2 in controlling MYCN expression in neuroblastoma." (PMID 33270844, 2020). "In this study, we observed a specific regulatory interplay between expression of Myc members in the MYCN-amplified neuroblastoma cells." (PMID 32483461, 2020). "In neuroblastoma, a genetic aberration of MYCN amplification is related to a poor prognosis and failure of therapy." (PMID 32660514, 2020). "MYCN amplification is the most frequent driver in neuroblastoma, occurring in ~20% of cases and conferring poor prognosis." (PMID 33056981, 2020). "Detection of amplification of the MYCN gene is essential for estimating treatment and prognosis of patients with neuroblastoma." (PMID 32896084, 2020). "MYCN genomic amplification is a biomarker of aggressive tumors in the childhood cancer neuroblastoma." (PMID 32409685, 2020). "Elevated ATF4 expression is a common feature of neuroblastoma cells with MYCN amplification and is responsible for the activation of the serine–glycine synthesis pathways essential for cell survival." (PMID 32310340, 2020). "AURKA and PLK1 are up-regulated by MYCN and are frequently overexpressed in MYCN-amplified neuroblastomas." (PMID 33194665, 2020). "Recent studies reveal that several super-enhancer harboring transcription factors including HAND2, ISL1, PHOX2B, GATA3, and TBX2 constitute a CRC that is essential for the MYCN expression and the survival of MYCN-amplified neuroblastoma cells." (PMID 33614505, 2020). "So, we tested the combinational prognostic effects of EIF4G1 expression and MYCN amplification in patients with neuroblastoma." (PMID 32593299, 2020). "On the other hand, NCYM also functions as a non-coding RNA and cooperates with CTCF to promote the progression of neuroblastoma by facilitating the expression of MYCN." (PMID 33194665, 2020). "We propose that MYCN amplification and ATRX mutations are incompatible in neuroblastoma, because both lead to DNA-replicative stress." (PMID 32060267, 2020).